NANOG (Nanog homeobox)
Diseases named in the same sentence as NANOG in open-access papers (continued):
Sharing a sentence is not in itself a finding about the gene and the disease.
cancer (continued). "Studies have shown that, the expression of NANOG in prostatic adenocarcinoma is related to the proliferation of cancer stem cells." (PMID 35686011, 2022). "NANOG enables cancer cells to acquire stem-cell-like properties like self-renewal and immortality, leading to growth expansion, tumor maintenance, metastasis formation, and tumor relapse." (PMID 35186145, 2022). "A plethora of cancer-associated markers such as CD133, CD44, ABCG2, aldehyde dehydrogenase, octamer binding transcriptional factor 4, SOX2, and NANOG have been reported in cancer stem cells." (PMID 35992863, 2022). "The varied enrichment of OCT4 (POU5F1), SOX2, and NANOG in different types of cancer cells demonstrated the diversity of CSCs localization." (PMID 36451812, 2022). "NANOG regulates the pluripotency of cancer cells and plays an important role in the evolution of PCSCs." (PMID 35812177, 2022). "This is supported by experimental studies that show inhibition of NANOG leading to inhibition of tumor initiation, suggesting the role of NANOG in cancer development." (PMID 35186145, 2022). "As a result, the in vivo tumorigenic potential (i.e., sphere-forming, anchorage-independent growth, cancer cells migratory, and drug resistance) were significantly reduced in the NANOG, and NANOGP8 knockout cell lines (KHOS and MNNG/HOS)." (PMID 35686011, 2022). "OCT4 and NANOG enhance malignancy in lung adenocarcinoma by inducing cancer stem cell-like properties and epithelial-mesenchymal transdifferentiation, and increased metastasis in breast cancer." (PMID 33453053, 2021). "Research reports from our group have detailed CD24 as a key regulatory molecule responsible for cancer stem cell induction via modulating the activity of CD49f and NANOG." (PMID 34680249, 2021). "Meanwhile, FOXJ1, negatively regulated by NANOG, exerts anti-cancer proliferation, migration, and invasion activity in OC43." (PMID 33785763, 2021). "NANOG is a stemness regulatory factor, which modulates carcinogenesis and multidrug resistance in malignant tumors." (PMID 33975615, 2021). "In agreement, some intratumoral signaling crosstalk, e.g., glucose restriction, up-regulate the expression of pluripotency related genes SOX2, OCT4, and NANOG, increasing cancer stem cells." (PMID 33805347, 2021). "Stem-cell-related pluripotency genes, such as OCT4, SOX2, KLF4, MYC, LIN28, and NANOG, are expressed in various types of cancer cells." (PMID 34488885, 2021). "The stemness-associated markers OCT4, NANOG, SOX2, KLF4 and c-MYC are expressed in numerous cancer types suggesting the presence of cancer stem cells (CSCs)." (PMID 34685477, 2021). "NANOG has been found to regulate cancer stem cells (CSCs) inside the cancer cells, which show a peculiar potential in tumor progression, heterogeneity, metastasis, recurrence, and drug resistance." (PMID 34528758, 2021). "Potential relationships with the expression of tumoral PD-L1 and cancer stem cell (CSC) markers (NANOG, SOX2, OCT4, Nestin and Podoplanin (PDPN)) are assessed." (PMID 34201050, 2021). "Short hairpin RNA (shRNA)-mediated NANOG knockdown in human gastric cancer cells decreased the characteristics of malignant cancer cells by increasing apoptosis and arresting cell cycle at the S phase." (PMID 34488885, 2021). "Elevated NANOG expression levels have been reported in many types of human cancers, including lung, oral, prostate, stomach, breast, and brain." (PMID 34638956, 2021). "Expression increase of VEGFA, PGE2S, COX2, EGFR, and NANOG in cancer cells was characteristic for the increase of resistance, as the sensitizing ratio was the opposite in the principal component analysis." (PMID 33671869, 2021). "OCT4, SOX2 and NANOG, as the embryonic stem cell transcription factors, transform cancer cells to stem-like cell phenotype in different tumor types." (PMID 34150636, 2021). "We showed that by inhibiting PKC activity, NANOG expression was upregulated in six human cancer cell lines." (PMID 35008480, 2021).
cancer (continued). "In another project from our group, we report that exogenous exposure to arsenic leads to malignant transformation in normal urothelial cells (HUC-1) and induces cancer stemness by upregulating OCT4/NANOG via the COX2/PGE2-SOX2 pathway." (PMID 34680249, 2021). "Even though NANOG is silenced in normal somatic cells, an aberrant expression is reported in a wide variety of cancers, correlating to poor survival." (PMID 34150761, 2021). "Aberrant NANOG expression has been also reported in many types of cancer including germline tumors, breast, prostate and colorectal cancers." (PMID 33471801, 2021). "Many self-renewal regulatory factors, such as OCT4, SOX2, BMI, and NANOG, are expressed in human malignant tumors, and they play an important role in carcinogenesis." (PMID 33925224, 2021). "In cancer cells, miR-21 downregulates the expression of transcription factor KLF3 to promote NANOG/OCT4-dependent cancer cell stemness program." (PMID 34591242, 2021). "It has been demonstrated that LINC-ROR regulates the pluripotency levels of TFs, including SALL4, LIN28, OCT4, SOX2, and NANOG via acting as a miRNA-145 sponge, leading to the preservation of hESCs and cancer stem cells undifferentiated status." (PMID 33745265, 2021). "Increased expression of VEGFA, PGE2S, COX2, EGFR, and NANOG in cancer cells was characteristic for the increase of resistance." (PMID 33671869, 2021). "In this feedforward transcriptional cascade, insulin growth factor (IGF) signaling increases STAT3-inducing activation, which, in turn, favors NANOG/Slug activity, and promotes cancer cells stemness and EMT." (PMID 34440220, 2021). "With 10 identifiers, we observed that these genes interacted with stemness genes such as SOX-2 and NANOG, genes important in cancer pathways such as STAT3, CTNNB1, EGFR, TNF, and CASP3, and immune genes such as IL2 and CD4." (PMID 34685742, 2021). "To this end, we employed the Cas9 technique and visualized both pMLCII (an amoeboid cell marker) and NANOG (a cancer stem cell marker)." (PMID 34532864, 2021). "Cancer stemness was analyzed by detecting the ability of migration and invasion, NANOG, OCT4, and SOX2 expression, ALDH activity and sphere formation." (PMID 34656128, 2021). "Altogether, we propose that NANOG+ cancer cells enriched by immunoediting drive preferential expression of HSP90AA1 via transcriptional regulation and undergo HSP90A accumulation in tumor cells." (PMID 31992715, 2020). "Here, we showed that antimycin A treatment enriched cells with very high expression of NANOG, which can correspond to cancer stem cells." (PMID 32664372, 2020). "Several studies investigating which NANOGs were expressed in cancer cells and tissues identified that NANOGP8 was the most prevalent NANOG expressed in many human cancers and contributed to their ‘stemness’ and proliferative capacity." (PMID 32580970, 2020). "Based on the observations that inhibition of IRX4 decreased NANOG-mediated cancer cell stemness, we examined the relationship between 1,25(OH)2D3/VDR and IRX4-induced NANOG expression." (PMID 32820157, 2020). "NANOG as a key transcriptional factor governs the self-renewal and pluripotency of stem cells, and cancer cells expressing NANOG also often exhibit stem cell properties." (PMID 32855630, 2020). "How NANOG functions in cancer is still a matter of debate, and its function in cancer cells seems to be highly context-dependent." (PMID 32197405, 2020). "The exosomal NANOG DNA has certain differences as compared to its normal counterpart that are of immense importance as a potential cancer biomarker." (PMID 32092088, 2020).
cancer (continued). "Analysis revealed that genes associated with cancer stem cells, such as POU5F1 (OCT4), SOX2, NANOG, BMI1, BMP2, CD44, SOX9, and ALDH1 were markedly upregulated in enzalutamide resistant cells." (PMID 33339129, 2020). "Elevated NANOG expression has thus been reported in various cancer types (lung, breast, colorectal, etc.), including in OSCC, and it is believed that it can be used as a prognostic biomarker." (PMID 32733958, 2020). "OCT4 and NANOG (stemness or pluripotency genes) in cancer hallmarks mainly enable the tumor replicative immortality and invasion that are crucial for tumor survival and growth." (PMID 33224314, 2020). "In conclusion, the role of NANOG in PCSCs is the same as in other cancers, i.e., controlling cancer stem cell growth." (PMID 33336042, 2020). "B lymphoma Mo-MLV insertion region 1 homolog (BMI1) advances the EMT and stemness of cancer cells via promoting NF-κB-mediated NANOG expression." (PMID 33066509, 2020). "Since NANOG is a crucial regulator of stemness, we asked if D2/NANOG co-expression targets both the bulk of tumor cells and the cancer stem cell (CSCs) population." (PMID 32197405, 2020). "It has also been shown that HA is involved in the maintenance of cancer stem cells (CSCs): in the presence of HA, tumor cells express stem-like markers, such as Oct4, Sox2, NANOG, and also ATP-binding cassette transporters." (PMID 33375053, 2020). "In light of our new data, we conclude that 1,25(OH)2D3 signaling-induced decreases in IRX4 inhibits NANOG-mediated cancer stem-like properties and gefitinib resistance in PC-9/GR cells." (PMID 32820157, 2020). "SOX2, OCT4, and NANOG are overexpressed in poorly differentiated malignant tumors and their expression overlaps with the characteristics of embryonic stem cells." (PMID 32766132, 2020). "NANOGP8, the human-specific NANOG retrogene that is often expressed in human cancers, was also induced during reprogramming, to very low but detectable levels, in a STAT3-dependent manner." (PMID 32580970, 2020). "NANOG was then found to associate with and be phosphorylated by FAK, and increased FAK-NANOG complexes promoted cancer cell pluripotency and invasive capacity." (PMID 32514188, 2020). "Considering the intimate connection between EMT and cancer stemness, we further examined the expression of six key biomarkers of cancer stemness (NANOG, SOX2, OCT4, CD44, ABCG2, BMI1)." (PMID 32863941, 2020). "Recently, the involvement of NANOG in tumorigenesis and cancer progression has drawn significant attention." (PMID 32754274, 2020). "A recent study revealed that TM4SF1 overexpression increases the expression of SOX2 and NANOG, sustains the manifestation of cancer stem cell traits, and drives metastatic reactivation in the lung and brain." (PMID 33153498, 2020). "The expression levels of cancer stemness markers, NANOG, OCT4, and SOX2, were significantly downregulated by stattic in FOXD2-AS1-overexpressing cells and vector cells." (PMID 31959918, 2020). "In this study, we discovered that TGF-β1/Smad3 signaling increased IRX4 expression and NANOG-mediated cancer cell stemness." (PMID 32820157, 2020). "Like ZSCAN4, embryonic factors OCT3/4, SOX2, and NANOG are reactivated in cancer and have further been classified as CSC markers that regulate self-renewal and contribute to tumor aggressiveness and metastasis." (PMID 32507861, 2020). "NANOG is a stem cell transcription factor, involved in the development of various human cancers including OSCC." (PMID 33643897, 2020). "The homeobox domain transcription factor NANOG, which is a key regulator of embryonic development and cellular reprogramming, has been reported to be broadly expressed in human cancers and exert a pro-tumorigenic effect." (PMID 32197405, 2020). "In summary, the roles of IRX4 downregulation increasing gefitinib cytotoxicity and inhibiting NANOG-mediated cancer stem-like properties were elucidated for the first time, to the best of our knowledge." (PMID 32820157, 2020).
cancer (continued). "It is therefore likely that upregulation of NANOG expression is critically related to tumorigenic cells in cancer." (PMID 32423137, 2020). "For example, NANOG is enriched in CD133+ or CD44+ cancer cells as compared to CD133- or CD44- cells 60-62." (PMID 32754274, 2020). "Overexpression of the Raf kinase inhibitory protein or AlkB family member 5, RNA demethylase (ALKBH5) can increase the expression level of NANOG, thereby participating in the regulation of cancer stem cell growth and reducing the capacity for tumor initiation." (PMID 33336042, 2020). "We have previously reported that cancer cell originated exosomes, including GBM, have NANOG and NANOGP8 DNA associated with them." (PMID 32092088, 2020). "Because CSCs are treatment-resistant cells responsible for the cancer recurrence and metastasis, modulated exosomal DNA of NANOG and NANOGP8 has a potential in assessing the efficacy of clinical therapy." (PMID 33137926, 2020). "Histone deacetylase 1 (HDAC1) transcription is induced by NANOG, which is key to these NANOG-dependent phenotypes of cancer cells." (PMID 32455616, 2020). "In H19-deficient cells, expression of cancer stem-cell markers Prominin-1 (CD133), homeobox protein NANOG (NANOG), Octamer-binding transcription factor 4 (Oct4), and Sox2 are downregulated." (PMID 32650527, 2020). "In conclusion, our study reveals a link among endogenous endocrine regulators of cancer, thyroid hormone and its activating enzyme, and the NANOG regulator of cancer biology." (PMID 32197405, 2020). "On the basis of previous studies of NANOG regulators in various cancers, we chose the following protein regulators for further analysis: AGR2, KLF4, NOTCH1, OCT4, and SOX2." (PMID 32733958, 2020). "The finding of mRNA in all samples and strong protein expression only in HG-dysplasia and carcinoma strongly suggest that NANOG expression is regulated at the post-transcriptional level." (PMID 33643897, 2020). "NANOG regulates stem-like traits in cancer cells, such as proliferation, self-renewal, anchorage-independent growth, motility, epithelial-mesenchymal transition (EMT), immune evasion, and chemoresistance." (PMID 31151327, 2019). "We investigated the ALDHhigh/low populations in both histotypes for the mRNA expression of SOX2 and NANOG, which are stemness-related genes in normal and cancer cells." (PMID 31921651, 2019). "Overexpression of these genes (OCT4, NANOG, and SOX2) in human cancer stem cells is associated with tumor transformation, tumorigenicity, and tumor metastasis." (PMID 31375149, 2019). "Whereas a number of current therapeutic strategies aim to target cancer stem cells, we chose to block NANOG function in human GBM since it is a key transcription factor that specifically regulates stemness in multiple contexts." (PMID 30846719, 2019). "Immunofluorescence analysis showed increased expression and nuclear co-localization of FRA1, phosphorylated STAT3, and NANOG protein in the cancer samples when compared with adjacent (para-carcinoma) normal tissues." (PMID 30804456, 2019). "The niche of IL6 stimulates the expression of IGF-1R and autocrinal IGF1 dependently in HBV-HCCs and strongly correlates with OCT4/NANOG expression, early recurrence, and cancer stemness features." (PMID 31505803, 2019). "ICAM1 was previously reported to contribute to the activation of not only NK cells but also CTLs, and NANOG expression was shown to induce CTL resistance in cancer cells." (PMID 31619256, 2019). "The mRNA levels of genes (CD133, OCT4, and NANOG) related to stemness of cancer cells were significantly down-regulated (p < 0.05)." (PMID 31307515, 2019). "It has been widely reported that the epithelial-to-mesenchymal transition (EMT)- and stemness-related genes including Slug, KLF4, SOX2, OCT4, and NANOG are overexpressed in human cancers and confer CSCs traits." (PMID 31526394, 2019).
cancer (continued). "It is evident that the core stem cell factors OCT4, SOX2, and NANOG play essential roles in maintaining the pluripotency and self-renewal of embryonic stem cells, adult stem cells, and cancer stem cells." (PMID 31375149, 2019). "Consistent with their roles in other cancer types, the transcription factors NANOG, OCT4, and SOX2 promote stemness features in colorectal CSCs." (PMID 31137841, 2019). "Nevertheless, since NANOG expression was only detected in 5 out of 12 OPMDs that subsequently progressed to carcinoma, this suggests that NANOG seems to partially contribute as a driver gene to promote OSCC tumorigenesis." (PMID 31484317, 2019). "LncRNA Oip5-as1 facilitates stem cell self-renewal in mouse by sponging mmu-miR-7 and modulating NANOG level, yet its role in cancer is less understood." (PMID 29728583, 2018). "Expression of cancer stemness-specific genes NANOG and POU5F1 was inhibited in sFRP4 OE cells, whereas sFRP4 SI cells showed elevation in NANOG and POU5F1 gene expression that was much higher than in the untreated U87 control." (PMID 30591679, 2018). "NANOGP8, one of the pseudogenes in NANOG gene family, contains an intact open reading frame and also said to be expressed in cancer tissues." (PMID 29689047, 2018). "The realization that the resistant cancer cells driving tumor recurrence after classical treatment express NANOG have prompted the development of NANOG inhibitors." (PMID 29971070, 2018). "The qPCR studies identified five mRNA (CA11, MEDAG, LAMA4, SPINT2, NANOG) and six miRNA (let-7b, miR23b, miR29a, miR30d, miR205, miR720) that were significantly differentially expressed between cancer ascites and peritoneal fluids." (PMID 29499737, 2018). "Prior studies have suggested that OCT4 and NANOG have a key role of tumorigenesis and prognosis of cancer." (PMID 30082842, 2018). "Apparently, the conversion of more mature cancer cells into CSCs (plasticity) requires epigenetic changes that allow re-expression of HLA class I. These findings suggest that CSCs expressing NANOG should be vulnerable for CD8 attack." (PMID 29971070, 2018). "Expression of the stem cell factors SOX2, OCT4, NANOG, and MYC has been linked to tumor malignancy in several cancers." (PMID 30510261, 2018). "It is worthy to note that PluriSin#1 preferentially induces NANOG-positive stem cell apoptosis but has little effect on differentiated cardiomyocytes derived from iPS, showing a promising clinical application for cancer therapy." (PMID 29907133, 2018). "c, Expression levels of markers related to cancer stem cells [nanog homeobox (NANOG) and SRY (sex determining region Y)-box 2(SOX2)] was assessed by western blot assay in both enriched spheres (SP) and monolayer parental cells (2D)." (PMID 30231942, 2018). "For instance, several stemness markers, such as OCT4, C-MYC, KLF4, NANOG, SALL4, and SOX2 are reported to be highly expressed in various cancers and associated with poor clinical outcomes of patients." (PMID 29747452, 2018). "NANOG is required for maintaining stem cell properties and is re-expressed in a wide array of cancers." (PMID 29971070, 2018). "Previous studies reported that CSC biomarkers such as NANOG, OCT4, SOX2, KLF4 and ALDH1A1 were associated with a poor prognosis in several cancers." (PMID 29615105, 2018). "Because cancer cells re-express NANOG when they regain stem cell properties, generation of immunological memory after DC vaccination against NANOG would help the immune system to cope with CSC plasticity." (PMID 29971070, 2018). "Further studies should also explore variances within modulated exosomal NANOG DNA among specific stages of cancer, to identify any prognostic implications." (PMID 29787607, 2018). "In this study, the combination panel (CD24, CD49f, and NANOG) yielded high sensitivity for cancer detection not only for NMIBC (80.9%), but also for low-grade UCB (80.0%)." (PMID 30327565, 2018).